IL1B (interleukin 1 beta)
Diseases named in the same sentence as IL1B in open-access papers (continued):
Sharing a sentence is not in itself a finding about the gene and the disease.
atherosclerosis (continued). "NLRP3 inflammasome and the downstream pro-inflammatory cytokines IL-1β and IL-18 are attractive pharmaceutical candidates for therapeutic intervention of atherosclerosis, and selectively neutralizing these cytokines has been shown to be available in the context." (PMID 35459215, 2022). "And, IL-1β mediates macrophage-macrophage-like VSMC crosstalk through regulating key transcription factors involved in macrophage-like VSMCs functional alterations during atherosclerosis progression." (PMID 36456628, 2022). "This study suggested that IL-1β per se might have multiple benefits in the late-stage murine atherosclerosis." (PMID 35563294, 2022). "IL-1β is a key cytokine in atherosclerosis, and IL-1β-/- mice were reported to have a 30% reduction in the size of atherosclerotic plaques compared with the control group, in addition, monoclonal antibodies against IL-1β inhibit plaque formation in apo E-/- mice." (PMID 35967399, 2022). "Increased Il-1β expression is particularly important in atherosclerosis." (PMID 36497101, 2022). "The importance of Il-1β in atherosclerosis was confirmed in the landmark CANTOS trial." (PMID 36497101, 2022). "Moreover, accumulating evidence has shown that NLRP3 activation products IL-1β and IL-18 both play an important role in the occurrence of atherosclerosis." (PMID 35844498, 2022). "In addition, L-18 share similar function with IL-1β, which tends to be considered as a proatherogenic cytokine in atherosclerosis." (PMID 36304814, 2022). "In addition, the expression of CAMs, as well as the release of IL-6 or IL-1β from endothelial cells, represents one of the earliest pathological changes in immune and inflammatory diseases such as atherosclerosis." (PMID 35456570, 2022). "Also, other studies have shown thatNLRP3, ASC, IL-1β, IL-18, and otherNLRP3 inflammasome components, with their respective products, aresignificantly expressed in patients with atherosclerosis." (PMID 39076616, 2022). "To determine whether macrophage inflammation is involved in Hcy-related atherosclerosis, we detected F4/80 (a positive marker of macrophages) and proinflammatory cytokines (IL-1β, IL-6, and TNF-α) in the aortic root of ApoE−/− mice." (PMID 34725437, 2022). "Considering the fact that inflammation has a key role in the development of atherosclerosis, we further investigated whether capsaicin administration could ameliorate inflammation in ApoE−/− mice, and the levels of IL-1β, IL-6, TNF-α were detected in serum." (PMID 36297020, 2022). "In addition to these, there are animal experiments and clinical trials showing that drugs target IL-1β in the treatment of atherosclerosis, including Anakinra, monoclonal antibodies, vaccines, and rilonacept." (PMID 36082127, 2022). "Taken together, IL-1β is detrimental and promotes early-stage atherosclerosis development but on the other hand animal models suggest that it is beneficial in an advanced stage of the disease to maintain plaque stability and avoid major cardiovascular complications." (PMID 35600479, 2022). "Interleukin (IL)-1β plays an important role in atherosclerosis pathogenesis." (PMID 35563294, 2022). "Previous research has highlighted the clinical significance of IL-1β during atherosclerosis." (PMID 36456628, 2022). "In addition, if the balance of IL1B is disturbed, it can also lead to the development of atherosclerosis." (PMID 35419117, 2022). "A recent study revealed that the H3K4me1 of the IL-1β promoter could be increased by the tumor suppressor gene SNF5 through the downregulation of KDM1A in macrophages, leading to enhanced IL-1β levels, thereby promoting the formation of atherosclerosis." (PMID 36552836, 2022).
atherosclerosis (continued). "In addition to CCL3, CCL4, and DUSP2, IL1B, known to be highly relevant in atherosclerosis, was highly upregulated in CM of HIV+CVD+ women." (PMID 36045343, 2022). "Nonetheless, the PXE-induced inflammasome activation suggests that involved genes may influence the severity of cardiovascular disease like IL1B has been shown to contribute to the progression of atherosclerosis." (PMID 34169069, 2021). "Furthermore, we demonstrated that pharmacological interventions targeting the UCP1/MMP/NLRP3 inflammasome–IL-1β axis are promising therapeutic strategies for the treatment of atherosclerosis in small- and large-animal models." (PMID 34878840, 2021). "Some risk factors such as dyslipidemia, oxidized lipids, and cytokines can activate polarization of M1 macrophages that secrete proinflammatory cytokines such as TNF-α, IL-6, IL-1β, and iNOS, thereby creating inflammatory environment and promoting the development of atherosclerosis." (PMID 34901005, 2021). "Besides production of IL-1β and other pro-inflammatory mediators, phagocytes carry out numerous functions that are dysregulated in atherosclerosis." (PMID 33790857, 2021). "Lipopolysaccharide (LPS), NEU1, and IL-1β act in a positive feedback loop as enhancers of inflammation in monocytes/macrophages and may therefore promote atherosclerosis and plaque instability." (PMID 34869700, 2021). "Canakinumab, an IL-1β inhibitor, suppressed the development of atherosclerosis." (PMID 34830282, 2021). "Thus, the excessive release of IL-1β and IL-18 attributed to pyroptosis is one of the factors that aggravate atherosclerosis, but meanwhile, the over-inhibition of inflammation also leads to plaque instability." (PMID 35096837, 2021). "This screening allowed us to identify a plasmatic signature associated with subclinical atherosclerosis specific to PLWH that included the upregulation of IL-18 and IL-1β and downregulation of TRAIL, three important proteins with known functions in atherogenesis." (PMID 33936102, 2021). "They suggest an atheroprotective role for IL-1β in late-stage atherosclerosis." (PMID 33800271, 2021). "Additionally, NLRP3 inflammasome can promote the conversion of IL‐18 and IL‐1β precursors into mature IL‐18 and IL‐1β, which plays a key role in atherosclerosis." (PMID 34331512, 2021). "Taken together, these data suggest that the IL-1β/ IL-1R1/IL-22 axis may play a key role in the aetiology of atherosclerosis." (PMID 34388961, 2021). "For example, in the HUVEC system, LUT-7G reduces the expression of IL-1β, which has been demonstrated to be a clinically applicable intervention to improve the cardiovascular outcomes, leading to a new use of anti-inflammatory therapies for atherosclerosis." (PMID 33525692, 2021). "TMAO drives atherosclerosis progression, in part, by regulating macrophage activation and foam cell formation, platelet activation, and aggregation, resulting in elevated expression of IL-1β, IL-6, and TNFα inflammatory cytokines." (PMID 33562334, 2021). "Inflammatory cytokine IL-1β is a key element in inflammatory signaling and atherosclerosis." (PMID 34831028, 2021). "Inflammation cells, monocytes and cytokines they release (such as TNF-α, IL-1β, IL-6) have also been found to play an important role in different cardiovascular pathological processes, such as atherosclerosis, myocardial infarction, myocardial remodelling and heart failure, and arrhythmias." (PMID 34957244, 2021). "It is also unclear whether the beneficial effect induced by anti-IL-1β therapeutics in the setting of atherosclerosis is related to the effect of these therapeutics on atherosclerotic vascular calcification." (PMID 34803503, 2021). "Alternatively, this group may benefit from IL‐1B inflammatory blockade, which has also been shown to be relevant to atherosclerosis in model systems of CHIP." (PMID 34050697, 2021).
atherosclerosis (continued). "As one of the most important multimeric protein complexes, NLRP3 inflammasome activation leads to increased cleavage of caspase-1 and downstream IL-1β production, and plays a pathological role in many diseases including diabetes, atherosclerosis and cardiovascular diseases." (PMID 34583676, 2021). "FAK was reported to regulate TNFα and IL1β signaling-induced vascular endothelial adhesion molecule expression and has been demonstrated to be a therapeutic potential in the treatment of vascular inflammatory diseases and atherosclerosis." (PMID 34093519, 2021). "Remarkably, IL-1β treatment increased profoundly the lipids accumulation and VSMCs foam cells formation highlighting the critical role of IL-1β in atherosclerosis progression as well as VSMCs foam cells formation, with consequences for atherosclerotic plaque stability." (PMID 35008765, 2021). "Therefore, in our opinion, high-concentration homocysteine affects the progression of atherosclerosis by increasing the secretion of proinflammatory cytokines secreted by PBMNCs, such as Il-1β, Il-6, RANTES, and by attenuating the secretion of Il-10." (PMID 34771080, 2021). "In addition to them, there are animal experiments and clinical trials demonstrating drugs targeting IL-1β in the treatment of atherosclerosis." (PMID 33362770, 2020). "The results of CANTOS suggested an important role of IL-1β in atherosclerosis." (PMID 33362770, 2020). "Although IL1β has been extensively studied and an antibody against this cytokine proved to be effective in attenuating atherosclerosis in a mouse model, the CANTOS trial showed as minimal as 15% reduction in the primary endpoint with an IL1β antibody (canakinumab) in a phase III clinical trial." (PMID 33324416, 2020). "Other studies indicate that lack of IL-1β decreases the severity of atherosclerosis in ApoE-deficient mice, and antibodies targeting mouse IL-1 have resulted in reduced atherogenesis; whereas, exogenous IL-1β increases intimal medial thickening." (PMID 33025148, 2020). "A large clinical trial, Canakinumab Anti-inflammatory Thrombosis Outcome Study (CANTOS) has proved the effectiveness of anti-inflammatory therapy in treating atherosclerosis and demonstrated the important role of interleukin-1β (IL-1β) in promoting atherosclerosis." (PMID 33362770, 2020). "Plenty of evidence has shown the important effect IL-1β exerts on atherosclerosis." (PMID 33362770, 2020). "In experiments involving non-high-fat or restrictive high-fat diet, it can often be proved that IL-1β signaling pathway could promote atherosclerosis." (PMID 33362770, 2020). "IL-1β is a known mediator of endothelial activation in the context of atherosclerosis." (PMID 32384773, 2020). "The authors demonstrated that TET2 loss of function in macrophages exacerbated NLR Family Pyrin Domain Containing 3 (Nlrp3) mediated Interleukin 1 beta (IL-1b) production which in turn accelerated atherosclerosis in a context of CHIP, thereby demonstrating that CHIP leads to increased inflammation." (PMID 32526214, 2020). "When evaluating the association between inflammatory markers and CIMT, a significant association with TNF-α was observed in the multivariate analysis, as the increase in IL1-β levels presented a greater chance of atherosclerosis with p-value close to significance." (PMID 31664319, 2020). "Links between NETs and cytokine release have already been documented, e.g. NETs may induce the transcription of IL-6 and pro-IL-1β genes in macrophages in early atherosclerosis." (PMID 32685129, 2020). "IL-1β signaling was reported to promote a Th17 response in CD4+ T cells in atherosclerosis." (PMID 32373127, 2020). "Furthermore, cholesterol crystals captured by macrophage yields inflammasome complex activation producing interleukin-1 beta to provide a feed forward mechanism to amplify atherosclerosis." (PMID 32891145, 2020).
atherosclerosis (continued). "In addition, monoclonal antibodies against IL-1β (canakinumab) and methotrexate were also confirmed as efficient for the treatment of atherosclerosis." (PMID 32733941, 2020). "Due to its blocking of IL-1β, it could be an important treatment for diseases with high grades of inflammation, such as ischemic injury, atherosclerosis and type 2 diabetes." (PMID 32650482, 2020). "Thus, the role of IL-1β in atherosclerosis is still believed to be detrimental in anti-inflammatory treatment, in addition to CANTOS, other off-target therapies have also been tried." (PMID 33362770, 2020). "In addition to IL-1β, IL-6, and TNF-α, other circulating peptides and cytokines are linked to atherosclerosis and cardiovascular disease." (PMID 32485823, 2020). "IL-1β is a proinflammatory cytokine mediator of atherosclerosis." (PMID 32373127, 2020). "More specific approaches to affect the interaction between clonal hematopoietic cells and the development of atherosclerosis could be represented an anti-inflammatory treatment affecting IL-1β or the restoration of TET2 function by vitamin C." (PMID 32825226, 2020). "This study has shown that attenuation of cardiac remodeling, fibrosis, alleviation of the aortic root and coronary arteries atherosclerosis is dependent on the reduction of IL-1β, TNF-α, IL-6 cardiac mRNA expression, and nuclear factor kappa B (NF-κB) activation pathway in RVX pre-treated group." (PMID 33301454, 2020). "IL-1β has multiple effects in all stages of atherosclerosis." (PMID 33362770, 2020). "SFA or cholesterol loading of macrophages is known to induce robust ER stress and mitochondrial oxidative stress, upstream of NLRP3 inflammasome activation and IL-1β and IL-18 secretion, resulting in an inflammatory response that drives atherosclerosis progression." (PMID 31422082, 2019). "IL-1β represents the tip of the iceberg; there are several other potential inflammatory mediators that could be directly targeted to halt atherosclerosis progression, such as by directly targeting the inflammasome, IL-1α, IL-6, IL-18, and IL-33, among others." (PMID 31672136, 2019). "A pro-inflammatory profile comprising SNPs in gene encoding regions of IL1B and IL1RN was further reported to confer an increased risk of atherosclerosis development and some studies have reported that IL1B and IL1RN polymorphisms are associated with genetic risk of IS." (PMID 31480765, 2019). "The NLRP3 inflammasome, a multiprotein complex including NLRP3, caspase-1, IL-1β and ASC, has been widely shown to be an essential step in cardiovascular disease and is linked to atrial fibrillation, atherosclerosis, diabetic cardiomyopathy and cardiac remodeling." (PMID 31354519, 2019). "This clinical benefit was achieved through IL-1β inhibition pointing toward tissue macrophage-derived elevated IL-1β production as a common denominator for situations with atherosclerosis like type 2 diabetes mellitus, chronic heart failure, and chronic renal disease." (PMID 30766533, 2019). "Increased TNF-α and IL-1β levels along with hyperglycemia helps to develop atherosclerosis." (PMID 30674322, 2019). "Both clinical and preclinical data support a link between IL-1β, inflammation, and atherosclerosis." (PMID 30873416, 2019). "The blockage of IL-1β results in the retarded development of acute and chronic inflammatory disorders, such as rheumatoid arthritis, psoriasis, atopic dermatitis, pharyngitis, aphthous stomatitis, and atherosclerosis, among others." (PMID 30970662, 2019). "Additionally, the levels of pro-inflammatory mediators (CD40L and IL-1β,-6,- 8), with major role in the atherosclerosis development, were measured in culture medium." (PMID 31068820, 2019).
atherosclerosis (continued). "Recently, clinical trials targeting IL-1β in patients with atherosclerosis using the monoclonal antibody canakinumab (anti-IL-1β) have shown a direct correlation with decreased incidence of lung cancer, decreased mortality, and better prognosis when compared to patients treated with placebo." (PMID 32039025, 2019). "Consistent with this notion, we observed enhancement of lipopolysaccharide-induced IL-1β release in SphK2−/− mice, which may contribute to aggravation of atherosclerosis." (PMID 31797978, 2019). "Although IRAK1 inhibition has not been tested directly in clinical CVD, the positive results recently reported for IL-1β blockade in atherosclerosis lend support to the testing of this hypothesis." (PMID 30279971, 2018). "Among them, inflammation is a well-known cause of cardiovascular events; indeed, atherosclerosis is an inflammatory process; numerous inflammatory molecules including hs-CRP, IL-6, IL-1β and TNF-α are elevated in patients with myocardial infarction or unstable angina." (PMID 29439738, 2018). "Clinical trials involving canakinumab, a monoclonal antibody against IL-1β, has shown a significant reduction of major cardiovascular incidents in patients with atherosclerosis, by reducing the total levels of plasma IL-6 and CRP compared to those given a placebo." (PMID 30333009, 2018). "IL-1β has a fundamental role in establishing and driving the pathogenesis of atherosclerosis." (PMID 29997514, 2018). "The inflammation hypothesis for atherosclerosis has been well accepted for decades in animal models and has been recently validated in humans with the effectiveness of an IL-1β antibody in preventing cardiovascular disease." (PMID 30405100, 2018). "Moreover, several inflammasome components NLRP3, ASC and IL-1β are elevated at the gene expression level, in a diabetic porcine model of atherosclerosis." (PMID 29515457, 2018). "Multiple studies have shown that IL-1β plays important roles in atherosclerosis." (PMID 30140264, 2018). "We aimed to investigate whether DHA supplementation in mice could alter vascular contractility via an IL‐1β–mediated mechanism, contributing to blood pressure reduction in experimental atherosclerosis." (PMID 29960988, 2018). "Higher expression of NLRP3, AIM2, and ASC could give rise to IL-1β and IL-18 secretion, promoting atherosclerosis and further destabilizing atherosclerotic plaques, which indicates their importance in cardiovascular disease pathogenesis." (PMID 30555415, 2018). "Although the role of inflammation in atherosclerosis has been identified over 150 years ago by Virchow, only recently has the “inflammation hypothesis” in atherosclerosis been specifically tested with an anti-inflammatory drug targeting IL-1β." (PMID 29662883, 2018). "The indirect connection between P2X7 and MMP9 through IL-1β indicates that A740003 could play a role in the regulation of MMP9 production aimed to atherosclerosis stabilization." (PMID 28687781, 2017). "VSMCs secrete copious IL-6 under stimulation conditions such as tumor necrosis factor (TNF)-α, IL-1β, platelet-derived thrombin, endothelin I, and lipopolysaccharide that they may be involved in the pathogenesis of atherosclerosis." (PMID 28531207, 2017). "Moreover, a growing bulk of pre-clinical data highlight the potential relevance of IL-1β in the development of atherosclerosis and cardiovascular dysfunction." (PMID 28659798, 2017). "In addition, deletion of IL‐1β or the use of monoclonal antibodies against IL‐1β inhibited the development of atherosclerosis in apoE−/− mice." (PMID 28409825, 2017). "In addition, Skoura and colleagues proved that S1PR2 expressed in macrophages of atherosclerotic plaque regulates inflammatory cytokine secretion (IL-1β, IL-18) and promotes atherosclerosis." (PMID 27965665, 2016). "Furthermore, the role of TNF-α, IFN-γ, IL-1β, IL-6, IL-8, IL-4 and IL-10 in the pathogenesis of atherosclerosis in carotid artery post-carotid endarterectomy has been documented." (PMID 27271180, 2016).